MMP1 (matrix metallopeptidase 1)
Diseases named in the same sentence as MMP1 in open-access papers (continued):
Sharing a sentence is not in itself a finding about the gene and the disease.
tumor (continued). "When optimized cut-off values were selected, the single expression level of IL1RN, MAL or MMP1 correctly predicted the tumor or normal nature of tissue samples in, respectively, 87, 86 and 88 cases out of the 92 tested samples." (PMID 19835631, 2009). "ROS are also involved in pathways whichprogress tumor growth by increasing the production of interleukin 8 (IL-8) andinducible nitric oxide (iNOS), and inducing the secretion of matrixmetalloprotease-1 (MMP-1)." (PMID 19390648, 2009). "MMP1 was the most promising gene of this study because it was overexpressed in tumor, highly dyregulated (500-fold) and tumor-specific." (PMID 19835631, 2009). "Among the overexpressed genes in tumor, MMP1 showed the highest order of magnitude (510-fold) and FN1 the lowest (2.6-fold)." (PMID 19835631, 2009). "Taken together, we have clearly demonstrated that MSCs with minimal migratory activities can be reverted by supplementing the cells with recombinant or exogenous MMP1 gene products, which are essential for the tumor-trophic migratory activities of MSCs." (PMID 19489099, 2009). "Two identified JNK targets in scrib- + RasACT tumours are the matrix metalloproteinase protein, Mmp1 [our unpublished observations,], and the integrin-associated scaffolding protein, Paxillin (this study)." (PMID 19778415, 2009). "We found the increase of the expression of latent and active protein forms of MMP-1 to be related to higher tumour grade." (PMID 19531263, 2009). "This immunohistochemical study confirms the phenotypic expression of MMP-1 in tumor cells and shows that its intensity increases as the tumor cells come in closer contact with the vascular wall." (PMID 18954439, 2008). "In this sense, overexpression of collagenase-1 (MMP1) and collagenase-3 (MMP13) has been associated with more aggressive tumors and poor prognosis in different tumor types." (PMID 19094243, 2008). "We suggest, based on the data presented here, that MMP-1-mediated connective tissue damage in the tumour matrix itself provides the stimulus for new vessel formation." (PMID 18443597, 2008). "In past studies from our laboratory, we showed that the epithelial tumour cells themselves, but especially the surrounding fibroblasts, produce large amounts of MMP-1." (PMID 18443597, 2008). "We found a trend of lower MMP1 levels with increasing tumour size (p = 0.07); and higher MMP8 levels with premenopausal status (p = 0.06) and NPI (p = 0.04)." (PMID 18366705, 2008). "For instance, the reverse correlation of plasma MMP1 expression with tumour growth is then in accordance with the established tumour growth promoting role of MMP1 in the tumour tissue." (PMID 18366705, 2008). "In relation to tumour progression, MMP-1 has received relatively little attention compared to the basement membrane-degrading proteinases (MMP-2, -9)." (PMID 17311017, 2007). "The expression of MMP-9 or TIMP-2 by tumour cells, MMP-1, 7, 9, 11, 13, or TIMP-3 by fibroblastic cells, and MMP-7, 9, 11, 13, 14, TIMP-1, or TIMP-2 by mononuclear inflammatory cells, was also significantly associated with a higher rate of distant metastases." (PMID 17342087, 2007). "Overexpression of MMP-1, MMP-2, and MMP-3 has been linked to poor prognosis, high tumour stage, and enhanced tumour invasiveness in patients with CRC." (PMID 17311017, 2007). "The concentration of MMP-1 in urine correlates with tumour stage and grade, a relationship confirmed in tissue samples in our study." (PMID 16465195, 2006). "MMP-1 mRNA was detected in the tumour cells of five of the six xenografts examined, the exception, surprisingly, being the MDA-MB-231 splenic metastasis." (PMID 16430785, 2006). "In bladder cancer patients, urinary MMP1 concentration has been reported to increase significantly with increased stage and grade of tumour." (PMID 15083203, 2004).
tumor (continued). "A previous study of urinary TIMP1 concentrations showed higher concentrations in muscle invasive compared with superficial tumours, and a lower MMP1 : TIMP1 ratio was found in invasive tumours." (PMID 15083203, 2004). "MMP-1 mRNA was detected in tumour cells and/or in stromal cells in all cases of SCC, four of six AKs adjacent to SCC and four of 16 AKs." (PMID 10362121, 1999). "High MMP1 expression not only predicts poorer clinical outcomes but may also facilitate disease progression by remodeling the tumor microenvironment." (PMID 41425594, 2025). "Given that MMP1-based therapies may lose efficacy as the disease progresses, early inhibition of MMP1 could effectively impede tumor advancement." (PMID 40287412, 2025). "Moreover, platelets co-localized with tumor cells secrete MMP-1/2/9, which degrades extracellular matrix components, weakening structural barriers and further promoting tumor invasion." (PMID 40723273, 2025). "CAF release of chemokine (C-X-C motif) ligand 1 and 2 (CXCL1 and CXCL2) also increases tumor invasion, with CXCL12 further increasing macrophage recruitment, and CXCL1 increasing tumor invasion via activation of matrix-metallopeptidase 1 (MMP1), also known as interstitial collagenase." (PMID 40872475, 2025). "Furthermore, certain chemokines secreted by platelets, particularly CCL3, can activate the matrix metalloproteinase-1 (MMP-1) pathway, promoting tumor cell invasion." (PMID 40723913, 2025). "The role of circ_0001859/miR-101-3p/MMP1 axis was validated in xenograft tumor models in vivo." (PMID 40666104, 2025). "Additionally, in cases with a poor prognosis, HIF1A-driven pathways, such as PI3K/AKT, TNF-α, and Wnt, promote tumour proliferation and survival by metabolic reprogramming, as well as upregulation of metastasis-promoting genes such as MMP1, TWIST2, and ITGB1." (PMID 41007296, 2025). "In addition, the expression of Matrix metalloproteinase (Mmp1), a well-established marker for tumor invasion, was significantly upregulated in the invasive leading edges of QykiACT/scrib−/− clones compared to WT or QykiACT clones (Fig. EV1A)." (PMID 40551010, 2025). "In vivo experiments in mice also revealed that silencing MMP1 effectively inhibited tumor growth." (PMID 41425594, 2025). "Given that MMP1 and S100A2 have been identified as important factors in the onset and development of PDAC, further research should investigate the role of MMP1/S100A2 in fostering a tumor-supportive microenvironment, particularly concerning CCL2+ macrophages and OMD+ fibroblasts." (PMID 40092486, 2025). "The reduction of KRAS may suppress matrix metalloproteinase (MMP1), MMP3, and MMP9, which are recognized as proteins associated with tumor metastasis, through a mechanism dependent on IL-17 signaling." (PMID 40486048, 2025). "Relative to the other AD samples, both AD5 and the AYA group exhibited higher expression of genes associated with aggressive tumor features and inflammation (e.g., CXCL2, TUBB3, RRM2, and MMP1) and lower expression of differentiation markers and metastatic regulators (e.g., KIT and NCAM1)." (PMID 41374320, 2025). "Collectively, this research underscores the critical role of MMP1 in tumor biology and immune modulation, offering valuable insights that could inform the development of innovative treatments and improve outcomes for tumor patients." (PMID 40394037, 2025). "Furthermore, the gene signature distinctive to the PanIN subset exhibited a robust enrichment in tumor samples characterized by elevated MMP1 expression in the TCGA PAAD dataset." (PMID 40092486, 2025). "Moreover, the knockdown of circ_0001859 remarkably suppressed tumor size and growth, suppressed MMP1 expression and promoted miR-101-3p expression in nude mice." (PMID 40666104, 2025). "This suggests that MMP1-mediated ECM degradation and associated signaling events may influence immune cell recruitment and distribution within the tumor, thereby modulating the immune landscape." (PMID 41425594, 2025).
tumor (continued). "In addition to its structural role, MMP1 significantly influences tumor-immune interactions by modulating immune cell infiltration and positioning within the tumor microenvironment (TME)." (PMID 40394037, 2025). "Additionally, small molecules targeting P4HA1 reduce tumor growth in colorectal cancer models possibly through inhibition of MMP1." (PMID 38659022, 2024). "Tissue Factor Pathway Inhibitor 2 (TFPI‐2), a Kunitz‐type serine protease inhibitor, impedes the invasion and metastasis ability of tumour cells via inhibiting the activities of Matrix Metallopeptidase 1 (MMP1), Matrix Metallopeptidase 3 (MMP3), plasmin and trypsin." (PMID 39462685, 2024). "In this study, we assessed the influence of SPHK1 and MMP1 on tumor immunity and observed that both SPHK1 and MMP1 inhibited the ability of T cells to kill cancer cells in vitro, while promoting HNSCC growth in vivo by facilitating tumor immune evasion in mice." (PMID 39629135, 2024). "Also, MMP-1 accumulated intracellularly during the cell cycle mitotic phase appears to protect from apoptosis, therefore promoting tumor cell survival, growth, and chemoresistance." (PMID 39063046, 2024). "For instance, matrix metalloproteinases (MMP1, MMP3, MMP10, MMP12), while traditionally associated with promoting tumor cell invasion and metastasis, have been shown in recent studies to facilitate ferroptosis in the right context by inducing lipid peroxidation." (PMID 39372411, 2024). "Moreover, MMP1 can stimulate tumor cell proliferation and angiogenesis by liberating growth factors and cytokines from the ECM, thereby enhancing the availability of oxygen and nutrients to malignant." (PMID 39600313, 2024). "MMP1 regulates the adhesion between tumor cells, promoting tumor invasion and metastasis." (PMID 38321558, 2024). "Besides, CD138 expressed on MM cells binds to type I collagen and promotes matrix metalloproteinase 1 (MMP1) production, thereby stimulating tumor invasion, bone resorption, and angiogenesis." (PMID 39087026, 2024). "Likewise, MMP1 (involved in tumor cell invasion) was ranked as one of the most up-regulated genes (log2FC = 8.16, q = 9.05E−19)." (PMID 38589501, 2024). "However, they significantly differed in terms of marker genes (AKR1C1, FOSL1, LIF, and THAP2 vs. WNT5A, GREM1, TNC, and MMP1), tissue origins (normal vs. tumor), and organ preferences." (PMID 38744958, 2024). "In addition, 100% of the primary tumor cells explanted from five distinct tumors exhibited cytoplasmic MMP1 expression." (PMID 38891088, 2024). "Importantly, the combination of SPHK1/MMP1 knockdown and anti-PD-1 therapy produces more obvious tumor suppression and further alleviates CD8+ T-cell exhaustion." (PMID 39629135, 2024). "Higher levels of MMP-1 prior to vaccination might, however, modify immune cell trafficking or modulate dendritic cell function to facilitate an anti-tumor immune response." (PMID 38812776, 2024). "In addition, the interaction between AGBL4 and MMP-1 highlights a potential connection to the inflammatory processes within the tumor microenvironment of GBM." (PMID 39007144, 2024). "MMP1 also mediates the invasion of circulating tumor cells into the tumor environment." (PMID 38580797, 2024). "The tumor tissue sections tested consistently positive for MMP1 by IF staining." (PMID 38891088, 2024). "In addition, the combination of SPHK1/MMP1 knockdown with anti-PD-1 therapy resulted in more pronounced tumor suppression." (PMID 39629135, 2024). "We documented up-regulation in the expression of IFN-γ, IL12p70, IL-18, IL-20, MIF, TNF-α, TSLP, BLC, Eotaxin-1, Eotaxin-2, IP-10, MIP-1a, MIP-3a, FGF-2, MMP-1, TNFRII and TWEAK, which are implicated in the modulation of inflammation, apoptosis, tumor growth, invasion, and angiogenesis." (PMID 38954024, 2024).
tumor (continued). "These included amplification of a cluster of MMPs on chromosome 11q22.3, including MMP1 and MMP3, which have been previously associated with tumour-induced muscle loss in drosophila models 32, as well as amplifications involving ADIPOQ (Adiponectin) on chromosome 3q27.1." (PMID 37045997, 2023). "TNC was mainly expressed in CAFs, while MMP1 was mostly expressed in tumor cells." (PMID 37007745, 2023). "Notably, mCAFs highly expressed tumor invasion-associated genes (FAP, MMP1, MMP14, and POSTN), commonly associated with ECM remodeling and cell migration during tumor metastasis, thus reflecting the importance of mCAFs in the metastatic TME." (PMID 37853464, 2023). "Genes such as MYBL2, TOP2A, and MMP1 were significantly upregulated in tumor tissues." (PMID 38124743, 2023). "Expression of DOHH, P4HA3 and MMP1 was assessed with qRT-PCR in tumor cases and the normal cases." (PMID 37957566, 2023). "Elevated levels of Mmp1 in tumor cells stimulate gbb expression and secretion." (PMID 35319749, 2022). "This reminds us that MMP1 expression in tumor cells might be related to the heterogeneity of different TC cells, and MMP1 was upregulated in ATC cells." (PMID 36479070, 2022). "In conclusion, the integrated bioinformatic analysis revealed that MMP1 might act as a regulator for tumor progression and dedifferentiation in PTC, which was confirmed via the in vitro experiments." (PMID 36479070, 2022). "High MMP1 expression was related to poor OS in 9 tumor types." (PMID 36727076, 2022). "MMP1 that's produced by tumor cells contributed functionally in hematogenous spread of SCC." (PMID 35444805, 2022). "Taking into consideration all these data, we may suggest that in bovine cutaneous fibropapillomas, MMP-1 low expression may be responsible of tumor development and migration ability." (PMID 36713871, 2022). "Mmp1 is secreted together with Gbb from the tumor, and both Mmp1 and Gbb can disrupt the BM/ECM of the fat body, which might contribute to increased lipid mobilization." (PMID 35319749, 2022). "Given that MMP-1 is an important mediator in UV-irradiated skin damage and the formation of wrinkles, it is important to further delineate the E(AH)-mediated alteration of specific signaling pathways that lead to the reduction of MMP-1 and inflammatory cytokine production." (PMID 36330743, 2022). "Moreover, MMP1 expression was positively and significantly related to immune score in 16 tumor types." (PMID 36727076, 2022). "MMP1, as a member of the matrix metalloproteinase family (MMPs), is an enzyme involved in extracellular matrix remodeling and plays an essential regulatory role in the interaction between tumor cells and the tumor microenvironment." (PMID 35692496, 2022). "However, although we explored the relationship of MMP1 expression with clinical outcome and tumor immune infiltration using several databases, this study still needs to go further to obtain more rigorous conclusions." (PMID 36727076, 2022). "In addition, a recent study of a larval neoplastic epithelial tumor (RasV12 dlgRNAi) model proposed that tumor-secreted Mmp1 contributes to host muscle wasting by disrupting the BM/ECM of muscle." (PMID 35319749, 2022). "MMP1 can cleave many components of the extracellular matrix and promote tumor proliferation." (PMID 36147444, 2022). "MMP1 expression was consistently elevated in tumor than normal tissues in LIHC (P < 0.001)." (PMID 35948625, 2022). "Taken together, these data showed that MMP1 expression was elevated in most tumor types from TCGA." (PMID 36727076, 2022). "In conclusion, our findings suggest that MMP1 is a potential regulator of tumor progression and dedifferentiation in PTC, and might become a novel therapeutic target for PTC, especially for more aggressive PDTC and ATC." (PMID 36479070, 2022).
tumor (continued). "Previous studies reported that aberrant expression of collagenolytic MMPs (MMP-1/-8/-13) and unbalancing between MMPs and TIMPs represent a critical step in tumor growth and invasion; however, studies regarding this topic in bovine cutaneous fibropapillomas are lacking." (PMID 36713871, 2022). "In this study, we used transcriptome data of two cohorts, the GEO cohort of PDTC/ATC and PTC, and the TCGA cohort of PTC to perform differential analysis and functional annotation to evaluate the role of MMP1 as a potential regulator of tumor progression and dedifferentiation in PTC." (PMID 36479070, 2022). "MMP-1, MMP-2, MMP-8, MMP-11, and MMP-13 are implicated in the regulation of tumor cell migration." (PMID 36776395, 2022). "We found higher expression of MMP1 in tumor tissues from DLBC, SKCM and UCS." (PMID 36727076, 2022). "MMP1 expression was higher in tumor tissues at translation level." (PMID 35948625, 2022). "Therefore, MMP1, 2, and 9 genes act as a driving force in tumor invasion/metastasis and the formation of neovascularization within tumors." (PMID 36147444, 2022). "We conducted xenograft tumor models to explore the function of MMP1 in vivo." (PMID 35426219, 2022). "Thus, it is reasonable to propose that EBV activate MMP1 in order to demolish the matrix barrier of tissues facilitating further tumour migration and invasion." (PMID 36272970, 2022). "MMP1 with a Δβ of −0.32 was selected for further investigation because it is an oncogene known to be crucial in tumor development and metastasis; however, its epigenetic regulation and molecular mechanisms that contribute to chemo-resistance have not been elucidated." (PMID 35267540, 2022). "Indeed, in a 3D Matrigel-based system, the interplay between the human macrophage U937 cell line and breast tumor cells caused, in U937, a significant upregulation of MMP1 and MMP9, both involved in tumor invasion via ECM degradation." (PMID 35205760, 2022). "As reported in prior studies, high MMP1 expression may promote the production of tumor-killing immune cells (aDC, NK CD56bright cells, macrophages, Th1/2, TFH, T helper cells and CD4+ T cells) and cause regional inflammation and fibrosis (monocyte and CAF)." (PMID 35948625, 2022). "We need more biological experiments to explore the specific mechanism of MMP1 in tumor progression." (PMID 36727076, 2022). "Finally, the involvement of MMP1 in tumor cell growth and drug resistance induction was examined using a xenografted mouse model." (PMID 35267540, 2022). "Second, we have not thoroughly explored the underlying mechanisms by which MMP1 exerts its tumor-promoting effects in PTC." (PMID 36479070, 2022). "Matrix metalloproteinases are a family of extracellular endopeptidases capable of degrading all extracellular matrix components, in which MMP-1 and MMP-2 are the two major components of the family and are believed to be mainly associated with tumor invasion and metastasis." (PMID 34976177, 2022). "Patients with tumor had a higher MMP1 expression level than tumor free patients (P < 0.001)." (PMID 35948625, 2022). "Tumour derived MMP1 was shown to induce ECM disruption in fat body and muscle in a drosophila cancer model, leading to muscle wasting, however, whether it promotes mammalian cancer cachexia is yet to be investigated." (PMID 36428623, 2022). "This speculation combined with the BP of cell–cell adhesion via plasma-membrane adhesion molecules would to some extent explain the outcomes of high expression of MMP1 in tumor tissues and poor prognosis in HCC patients." (PMID 35948625, 2022). "In HNSCC, there were several reports about MMP1 and its effects on tumor progress." (PMID 35426219, 2022). "Our previous study showed that XFZYD inhibits tumour cell migration by regulating MMP1 expression." (PMID 35903326, 2022). "MMP1 expression in PTC tumor tissues was significantly higher than that in normal thyroid tissues, whether they were paired samples or not." (PMID 36479070, 2022).